HMGA2-AS1 (HMGA2 antisense RNA 1)
Synonyms: RP11-366L20.2
Gene: Long non-coding RNA gene on chromosome 12 (65,851,340 to 65,882,167, reverse strand). Ensembl gene ENSG00000197301.
Diseases named in the same sentence as HMGA2-AS1 in open-access papers:
HMGA2-AS1 is named in the same sentence as 1 disease in open-access papers, as found by Europe PMC text mining. Sharing a sentence is not in itself a finding about the gene and the disease.
HMGA2-AS1 shares sentences with these, for which no sentence is quoted: cancer (1 paper).